EGFR (epidermal growth factor receptor)
Diseases named in the same sentence as EGFR in open-access papers (continued):
Sharing a sentence is not in itself a finding about the gene and the disease.
breast carcinoma (continued). "One of the key findings of our large cohort analysis was that breast cancer EGFR mutations were more common among women of East Asian ancestry, although these mutations were rare in all populations." (PMID 41162424, 2025). "In conclusion, in this study, we focused on understanding the mechanism of autocrine loops of AREG and why EGFR+ and ER+ breast cancer is associated with poor patient prognosis." (PMID 40422206, 2025). "This is in line with other studies, suggesting that EGFR overexpression in breast cancer is associated with a larger tumor size, reduced tumor cell differentiation, and poor clinical outcomes." (PMID 40150035, 2025). "In particular, we focused on understanding the mechanism of autocrine loops of AREG and why EGFR+ and ER+ breast cancer patients is associated with poor prognosis." (PMID 40422206, 2025). "We previously reported that the level of EGFR expression is directly associated with the survival rate of estrogen receptor-positive (ER+) breast cancer patients." (PMID 40422206, 2025). "Based on the low mutation and high expression of EGFR in cancer, effectively limiting the expression of EGFR protein is conducive to inhibiting the progress of breast cancer." (PMID 38706904, 2024). "High EGFR expression and low p21 expression is associated with worse prognosis in breast cancer patients." (PMID 39698031, 2024). "Our results disclosed that higher expression of PTGS2/ESR2/EGFR/JUN/MMP2 genes’ signature associated with the most aggressive breast cancer subtypes donating by basal breast cancer (P < .00001) and the ER-negative breast tumors ( P < .00001)." (PMID 39707884, 2024). "Incubation with the sialyltransferase inhibitor (STi) P-3Fax-Neu5Ac reduced sialylation on two breast cancer cell lines, rendering these cells more susceptible to macrophage mediated phagocytosis by EGFR or HER2 antibodies." (PMID 39659795, 2024). "Previous studies have reported a significant association between EGFR expression and younger age or premenopausal breast cancer cases." (PMID 39405290, 2024). "Nonetheless, EGFR protein expression via IHC has been strongly associated with gene amplification in lung adenocarcinoma and breast cancer when detected by fluorescence and chromogenic ISH, respectively." (PMID 39123483, 2024). "Subsequent studies show the association of GD3 with EGFR and activated EGFR signaling in breast CSCs and breast cancer cell lines." (PMID 39329960, 2024). "In breast cancer, EGFR positivity has been associated with increased FOXP3+ regulatory T cells, which are known to suppress antitumour immunity." (PMID 38744099, 2024). "Other EGFR inhibitors such as afatinib, dacomitinib, lapatinib, neratinib, osimertinib, and vandetanib are used in various cancers such as NSCLC, small cell lung cancer, and breast cancer and target EGFR mutations." (PMID 39337925, 2024). "For example, EGFR-targeting exosomes loaded with anti-tumor miRNA let-7a caused significant tumor regression in an EGFR-expressing xenograft breast cancer mouse model, supporting the therapeutic potential of this approach." (PMID 39682778, 2024). "On the other hand, other studies have reported a significant association of EGFR over-expression with high-grade tumors in invasive types of breast carcinoma." (PMID 39405290, 2024). "Previous studies have reported an association between EGFR expression and a poor response to tamoxifen treatment in breast cancer." (PMID 39405290, 2024). "Mutations in the EGFR gene and its amplification are associated with colorectal, head and neck, non-small cell lung, genitourinary, and breast cancers." (PMID 38374954, 2024). "Margin status, American Joint Committee on Cancer (AJCC) stage, hypoxia status, estrogen receptor/progesterone receptor (ER/PR) status, NFIL3, SERPINE1, EGFR, and risk score were identified as independent prognostic indicators for breast cancer patients." (PMID 38500661, 2024).
breast carcinoma (continued). "Of note, EGFR overexpression is more prevalent in TNBC than other breast cancer subtypes and is associated with shorter survival." (PMID 39356138, 2024). "As reported, activation of Src kinase in some breast cancer cells leads to the phosphorylation of EGFR and causes the downstream effect." (PMID 38924082, 2024). "Studies have shown that EGFR signaling is closely linked to breast cancer development and resistance to cytotoxic drugs." (PMID 39723390, 2024). "We also identified an association of EGFR with a higher risk of breast cancer, which is inhibited by a variety of monoclonal antibodies in the treatment of breast cancer." (PMID 38684708, 2024). "Increased expression of EGFR is also associated with resistance to anti-HER2-targeted therapy in HER2+ breast cancer cases." (PMID 39405290, 2024). "BIRC6 has demonstrated overexpression in triple-negative human breast cancer cells and tissues, positively correlated with epidermal growth factor receptor (EGFR), and associated with poor patient survival time." (PMID 38951817, 2024). "The expression and activation of EGFR in breast cancer have been closely associated with specific transcription factors and metabolites." (PMID 39796003, 2024). "Although recent advancements in the development of anti‐EGFR compounds have shown partial efficacy in mitigating breast cancer metastasis still there exist limitations due to the mutations in the EGFR gene resulting in resistance to these inhibitors." (PMID 38522013, 2024). "The drug primarily targets HER2 and EGFR, both of which are overexpressed or mutated in certain types of breast cancer." (PMID 38611728, 2024). "GD2 was also identified as a cancer stem cell-specific marker from human breast cancer cell lines and patient samples, and GD3 was associated with activated EGFR signaling in both breast CSCs and breast cancer cell lines." (PMID 37954075, 2023). "As a key player downstream of EGFR, a tight association between EGFR and PIP5Kγ in the progression of breast cancer is found." (PMID 38156113, 2023). "Obesity results in cross-talks between leptin, ER-α receptor, IGF signalling and the transactivation of EGFR, which is thought to increase the risk of postmenopausal breast cancer." (PMID 37047163, 2023). "EGFRvIII mutations were also seen in 67.8% of primary breast cancers, and 57.1% of infiltrating breast cancers co-expressed wild-type EGFR and EGFRvIII." (PMID 38137520, 2023). "For example, EGF causes co-internalization of EGFR/α2β1 in platelets, EGFR/αVβ3 in fibroblasts, and EGFR/αVβ6 in breast cancer cells." (PMID 37519303, 2023). "About half of them in BL1 and BL2 were overlapping, such as LYN, JAK2, SYK, and EGFR, which were reported to be associated with the aggressiveness of breast cancer, particularly in TNBC." (PMID 36672350, 2023). "For example, heterodimerization of HER2 with either HER3, HER4, or EGFR has been associated with breast cancer cell growth, treatment resistance in preclinical studies, and worse outcomes in patients with ER+ breast cancer." (PMID 37575061, 2023). "In BCN, EGF-EGFR pair was identified as the key regulator (EGF interactions = 152, EGFR interactions = 358, total number of interactions = 510), which has been known to be associated with poor prognosis in breast cancer." (PMID 37566630, 2023). "EGFR overexpression has been observed in 15–30% of breast carcinomas and has been associated with large tumors and poor clinical outcomes." (PMID 38203378, 2023). "The proto-oncogene epidermal growth factor receptor (EGFR) plays an important role in human breast cancer as expression of its phosphorylated form is associated with increased angiogenesis and metastasis." (PMID 37835752, 2023). "Neratinib is another multikinase inhibitor that can potentially block the activity of HER2, HER4, and EGFR and is reported to be implicated in breast cancers." (PMID 37910519, 2023).
breast carcinoma (continued). "In malignant canine mammary carcinomas, overexpression of EGFR is associated with tumor size, necrosis, mitotic grade, histological grade of malignancy, tumor relapse, distant metastasis and clinical stage." (PMID 37835752, 2023). "Overexpression of EGFR has been observed in 15%–30% of breast carcinomas and is associated with large tumor size and poor clinical outcomes in BC59." (PMID 36882618, 2023). "Type III EGF receptor deletion-mutation (EGFRvIII) is the most common EGFR mutation in breast cancer, and it plays a pivotal role in cancer progression." (PMID 38090376, 2023). "Genetic aberrations of upstream regulators, such as activating mutations of PI3K, Ras, b-Raf, loss of function mutations of PTEN, overexpression of EGFR, have been shown to be common in breast cancer and play an important role in its dysregulation." (PMID 37596623, 2023). "Cancer organoids with breast cancer 2 genes, EGFR, and EGFR‐mutant/MSC‐epithelial transition (MET)‐amplified mutations responded better to laparib, erlotinib, and crizotinib, respectively." (PMID 37119028, 2023). "Abnormal EGFR expression or mutations in breast cancer are associated with aggressive tumor behavior and resistance to treatment." (PMID 37885828, 2023). "Targeted NGS genetic profiling revealed a rare EGFR T790M mutation in this patient's primary breast tumor tissue, which has only been reported previously in breast cancer (BC)." (PMID 37554157, 2023). "Collectively, our results demonstrate that the aggressiveness of breast cancer with EGFR and HER2 co-expression is associated with CCL2-induced recruitment of TAMs." (PMID 36674955, 2023). "It has been observed that nimotuzumab enhances the radiosensitivity of tumor cells in lung and breast cancer by blocking nuclear translocation in EGFR and inhibiting repair caused by radiation-induced DNA damage." (PMID 36814816, 2023). "Further studies to clarify the crosstalk of these pathways and the molecular mechanisms underlying the cooperative action of autophagy and EGFR/HER2 signaling to regulate breast cancer cells’ endocrine resistance and phenotype are required." (PMID 37575061, 2023). "It has been established that the most clinically aggressive subtypes of breast cancer, are also associated with EGFR overexpression, while in ERα-positive breast cancer, IGF-IR is present at high levels and its action is correlated to ER status." (PMID 35719919, 2022). "miR-338 and miR-30a are EYA2 regulators, and their downregulation increases EYA2 expression in breast cancer, and its reduction and epidermal growth factor receptor (EGFR) downregulation have been associated with lung metastasis." (PMID 35087589, 2022). "We found CAV1 in TCGA and GOBO to be associated with basal subtype, EMT, EGFR expression, and BRCAness, in line with others, all common in ER– breast cancer." (PMID 35660849, 2022). "The germline variant P1275L was observed in myeloproliferative neoplasms and in EGFR‐mutated tumors, but its role in both prostate and breast cancer should be further investigated." (PMID 35347810, 2022). "While Myoferlin plays an important role in the degradation of epidermal growth factor receptor (EGFR) in breast cancer, loss of this gene activity leads to a change in cell motility, i.e., reduced velocity of cell migration." (PMID 35330493, 2022). "The EGFR mutation status of patients with breast cancer can be well predicted based on enhanced MRI data and pathological data." (PMID 35663041, 2022). "The overproduction of EGFR is strongly associated with several types of cancer progression like ovarian cancer, breast cancer, and colon cancer." (PMID 35807270, 2022).
breast carcinoma (continued). "In previous proteomics studies, increased levels of the epidermal growth factor receptor were discussed as a risk predictor for future breast cancer diagnosis among women using MHT." (PMID 35033985, 2022). "We analyzed the relationship between EGFR mutation and breast cancer subtype and found that ER-positive patients were more likely to have EGFR mutations." (PMID 36313724, 2022). "In breast cancer, the increased core fucosylation of EGFR was associated with an increased dimerization and phosphorylation, resulting in increased EGFR-mediated signaling, promoting tumor growth." (PMID 35744954, 2022). "Gynecologic cancers are known to harbor low rates of actionable mutations, especially in comparison to lung, colon, and breast cancers which frequently express alterations in EGFR, KRAS, and HER2, respectively." (PMID 35267660, 2022). "As shown, all examined breast cancer cell lines show differential expression genes of TGFα-EGFR signaling which is associated with WWOX protein level." (PMID 35290621, 2022). "Another study in patients with high-risk primary breast cancer demonstrated that EGFR expression was associated with worse prognosis, specifically when co-expressed with HER2." (PMID 36291900, 2022). "TGFα-EGFR signaling was found to be significantly affected in all examined breast cancer cell lines in response to estrogen and strongly associated with the level of WWOX expression, especially in ER-positive MCF7 cells." (PMID 35290621, 2022). "In breast cancer, there are also some studies describing the importance of EGFR mutation status in the diagnosis and treatment of breast cancer." (PMID 35663041, 2022). "Aberrant EGFR is associated with aggressive clinical behavior in breast cancer; moreover, elevated EGFR levels increase the likelihood of developing ER-positive breast cancer." (PMID 36147483, 2022). "The authors stated that cells in high stiffness had increased expression of Mena, an invadopodia protein associated with metastasis in breast cancer, as a result of EGFR and PLCγ1 activation." (PMID 35268340, 2022). "Current evidence suggests an association between low baseline serum EGFR and shorter survival or reduced treatment responses in patients with advanced breast cancer." (PMID 35663041, 2022). "For example, epidermal growth factor receptor (EGFR) mutation has been reported as a driver of breast cancer." (PMID 36237897, 2022). "IGF-1R signal pathway is highly associated with resistance to the EGFR inhibitors in breast cancer cells." (PMID 35399718, 2022). "EGFR mutation in breast cancer patients is increasing and identified using the Sanger sequencing process." (PMID 36457709, 2022). "Loss of the H3K27me3 signal is associated with the upregulation of several breast cancer oncogenes, such as those encoding epidermal growth factor receptor (EGFR) or insulin like growth factor binding protein 3 (IGFBP3) involved in tamoxifen resistance." (PMID 35453496, 2022). "The role of EGFR dysregulation or mutation in cancer etiology, particularly breast cancer, has been proposed previously." (PMID 36686654, 2022). "Several studies have reported that overexpression of EGFR is common in breast cancer patients and is associated with decreased survival." (PMID 36313724, 2022). "Amplification of the ERBB2 gene was found in 20% of breast cancer cases and a mutated version of the epidermal growth factor receptor (EGFR) gene in 30% of glioblastomas." (PMID 33806009, 2021). "Current evidence indicates associations between low baseline serum-EGFR and shorter survival or reduced response to treatment in patients with advanced breast cancer, especially in patients with estrogen and/or progesterone receptor-positive tumors." (PMID 33356806, 2021). "To elucidate novel mechanisms and therapeutic strategies to overcome EGFR/HER2 therapy resistance, we created syngenic SKBR3 human breast cancer cell variants resistant to gefitinib (anti-EGFR) or lapatinib (anti-EGFR/HER2)." (PMID 34074257, 2021).
breast carcinoma (continued). "Studies found that patients with HER2−/HR− tumors present relatively higher expression of EGFR, and EGFR increases the risk of brain metastases in breast cancer patients." (PMID 34945169, 2021). "EGFR expression in breast cancer is associated with an aggressive phenotype, higher proliferation rate and greater genomic instability." (PMID 33804477, 2021). "HGF released from CAFs activates Met in cancer cells, causing a resistance to epidermal growth factor receptor (EGFR) TKIs in lung and breast cancers." (PMID 33918653, 2021). "Although the association between 8p deletion and expression of DUSP4 in RCC has not been studied, loss of 8p was associated with downregulation of DUSP4 in breast cancer and EGFR-mutant lung adenocarcinoma." (PMID 34679636, 2021). "Here, we report the engineering and testing of BiMAb and bifunctional TNFL fusion proteins targeting various well-established breast cancer-associated TAAs, including EGFR, HER2, CEA, EpCAM, and the tumor stroma antigen FAP." (PMID 34484225, 2021). "Diarrhea is frequently caused (75%) by lapatinib, an (epidermal growth factor receptor) EGFR/HER2 dual tyrosine kinase inhibitor for HER2+ advanced breast cancer." (PMID 34234854, 2021). "EGFR signaling has been directly linked with components of the fibrinolytic system, for example, in breast cancer and glioblastoma." (PMID 33886813, 2021). "EGFR/ErbB2 are members of the epithelial growth factor receptor family, gefitinib and lapatinib are clinically proven effective in targeting NSCLC with EGFR mutation and ErbB2 + breast cancers respectively." (PMID 34108040, 2021). "HDAC2 enables the motility of breast cancer cells by upregulating Matrix Metalloproteinase 2 (MMP2) and N-cadherin and HDAC3 associates with Epidermal Growth Factor Receptor (EGFR) and c-Src to promote breast cancer cell invasion." (PMID 33803458, 2021). "EGFR, a transmembrane protein, often serves as a marker associated with larger tumor sizes, poor differentiation and poor prognosis in breast cancer." (PMID 34797831, 2021). "Previous results have indicated a potential strong association between the expression of SHP-1 and EGFR in human breast cancer." (PMID 34591414, 2021). "IL-4-expressing CD4+ T cells were previously shown to promote pulmonary metastasis of breast cancer by directly acting on tumor-associated macrophages, which enhance metastasis through activating epidermal growth factor receptor signaling in cancer cells." (PMID 34707103, 2021). "The cytotoxicity of EGF-modified PMBN-paclitaxel complexes (EGF-PMBN-PTX) was evaluated in the EGFR-overexpressed or -deficient BT-20 breast cancer cell line, A431 squamous carcinoma cell line, and H69 small cell lung cancer cell line." (PMID 33530291, 2021). "TSA treatment was also associated with reduced EGFR expression in MDA-MB-468 breast cancer and A431 epidermoid carcinoma cell lines, as well as head and neck squamous cell carcinoma (HNSCC) cells." (PMID 33976119, 2021). "TNBCCs (Triple-negative breast cancer cells) often express epidermal growth factor receptor (EGFR) and it is associated with poor prognosis." (PMID 34070945, 2021). "Immunohistochemistry and The Cancer Genome Atlas database were used to investigate the clinical association between SHP-1 and EGFR in human breast cancer." (PMID 34591414, 2021). "Taken together, we show that overexpression of UCH-L1 contributes to loss or reduction of ERα in breast cancer, and this is mediated by its deubiquitinating and stabilizing effects on EGFR, which transcriptionally represses the expression of ERα." (PMID 32042339, 2020).